Y_RNA (Y RNA )
Gene: Miscellaneous RNA gene on chromosome 14 (50,086,982 to 50,087,083, forward strand). Ensembl gene ENSG00000251792.
Homologues: Paralogues in human: Y_RNA (93% identical), Y_RNA (92% identical), RNY3 (91% identical), Y_RNA (91% identical), RNY3P1 (90% identical), Y_RNA (90% identical), Y_RNA (89% identical), RNY3P11 (88% identical), Y_RNA (88% identical), RNY3P16 (87% identical), Y_RNA (87% identical), RNY3P14 (86% identical), and 98 more.